IL6 (interleukin 6)
Diseases named in the same sentence as IL6 in open-access papers (continued):
Sharing a sentence is not in itself a finding about the gene and the disease.
tumor (11,758 papers, 1992 to 2026). "Increased circulating IL-6 and IL-8 were consistently associated with tumor burden, advanced disease, and reduced survival." (PMID 41745410, 2026). "Preliminary data suggest anti‐IL‐6 therapy reduces weight loss and inflammatory symptoms, indicating benefits for tumor‐related neurological/metabolic complications." (PMID 41583906, 2026). "Biomarkers such as 8-hydroxy-2'-deoxyguanosine, malondialdehyde, F2-isoprostanes, C-reactive protein, interleukin-6, and tumor necrosis factor-α were frequently associated with tumor stage, prognosis, and treatment response." (PMID 41900943, 2026). "Distinct subtypes—such as LRRC15+ myofibroblastic CAFs (myCAFs) implicated in exclusion, versus IL-6-driven inflammatory CAFs (iCAFs)—exhibit divergent effects on tumor immunobiology." (PMID 41601669, 2026). "Tumor-Associated Fibroblasts (CAFs) inhibit the polarization of NK cell cytotoxic granules through cytokines such as Interleukin-6 (IL-6)." (PMID 41607548, 2026). "In the context of neoplasia, the production of growth factors such as GM‐CSF and G‐CSF, along with inflammatory cytokines like IL‐1β, IL‐6 and IL‐17, is increased by tumour cells, tumour‐infiltrating leukocytes and tumour‐associated stromal cells." (PMID 41503514, 2026). "Hepatic LRG1 induced by tumor-associated inflammation via IL-6/STAT3 signaling promotes liver metastasis through the formation of TGFBR/PI3K/AKT axis-driven neutrophil extracellular traps (NETs)." (PMID 41963620, 2026). "This study aimed to investigate the expression of inflammaging-related markers in RCC tissues, focusing on the role of PTX3, IL-6, and senescence-associated proteins in the tumor microenvironment." (PMID 41681886, 2026). "Chrzanowska and colleagues developed ciprofloxacin-fatty acid conjugates that notably decreased IL-6 secretion in cancer cells, potentially inhibiting tumor progression and inflammation-associated cancer development." (PMID 39861135, 2025). "Elevated IL-6 levels are associated with increased tumor burden, resistance to apoptosis, and poorer prognosis." (PMID 41049014, 2025). "IL-6 and IL-8, in particular, have been linked to tumor growth and neovascularization, and their overexpression has been correlated with poor clinical outcomes in NSCLC." (PMID 41303495, 2025). "High levels of IL-6 in tumor tissues were found to be a risk element for ESCC patients’ prognosis by Cox regression analysis (HR=1.72, 95%CI: 1.13-2.61, P=0.011)." (PMID 40433391, 2025). "In patients with lung and colorectal cancers, activin A levels correlate with inflammatory markers like CRP,305 which is known to associate with IL‐6—a procachectic cytokine produced by some tumor cells." (PMID 39764565, 2025). "Although IL-6 is commonly associated with tumor promotion and immunosuppression, emerging evidence suggests that it can also support antitumor immunity under certain yet not fully elucidated circumstances." (PMID 39653766, 2025). "Lastly, a study on prostate cancer demonstrated that YY1 is highly expressed in M2-polarized tumor associated macrophages, where it promotes tumor progression by upregulating IL-6 expression." (PMID 41327312, 2025). "Within the tumor microenvironment, tumor cells and associated stromal cells, such as macrophages and fibroblasts, secrete pro-inflammatory cytokines (e.g., IL-6, TNF-α, IL-1β)." (PMID 39836268, 2025). "IL-6, a proinflammatory cytokine in the tumor microenvironment, is linked to higher disease severity and worse clinical outcomes in cancer patients." (PMID 41307829, 2025). "A similar mechanism is more pronounced in the TME: tumor-associated macrophages (TAMs) are stimulated by proinflammatory factors such as IL-6 and TNF-α to upregulate LDHA expression through HIF-1α, resulting in lactate accumulation." (PMID 40843350, 2025). "IL‐6 is commonly associated with chronic inflammatory responses in the tumor microenvironment, where it regulates immune cell function and promotes immune evasion of tumors." (PMID 41316520, 2025).
tumor (continued). "To evaluate potential off-target effects, we quantified serum levels of IL-6, TNFα, and TGFβ, the key cytokines associated with tumor progression." (PMID 40475010, 2025). "Under IL-6 deficiency, cytotoxic T cells accumulated at the tumor site, with more IFN-γ-producing T cells, indicating that IL-6 mediates CD8+ T cell exhaustion and affects their quantity." (PMID 40433391, 2025). "Reduced tumor cell susceptibility to CD8+ T-cells was associated with increased IL-6 expression and reduced TNF-α and IFN-γ levels." (PMID 39883638, 2025). "IL-6 has been implicated in promoting multiple aspects of tumor progression, including cell proliferation, epithelial-mesenchymal transition (EMT), migration, invasion, and metastasis." (PMID 41373438, 2025). "Regulatory M2b macrophages express pro-inflammatory cytokines such as IL6 and TNFα and have been found to be a subset of tumor-associated macrophages (TAMs) that promote growth, invasion, and recurrence of tumors." (PMID 40470186, 2025). "Individual tumor analysis showed that higher IL-6 was associated with both irAEs occurrence and poor prognosis (DCR, PFS, OS) in ESCC patients, and with irAEs occurrence and poor prognosis (DCR, PFS) in GAC patients." (PMID 40519900, 2025). "The expression of IL-6 mRNA and protein was directly correlated with advanced tumor stage and its elevated expression was associated with increased recurrence and decreased survival rate." (PMID 40317079, 2025). "In this context, high concentrations of IL-6 are associated with a cellular microenvironment that benefits the growth of tumor cells in various types of cancer, such as lung, mammary gland, and colon, among others." (PMID 40722593, 2025). "In brain tumors, M1 macrophages can directly phagocytose or kill tumor cells through antibody-dependent cytotoxicity and cause vascular damage and tumor necrosis by generating a variety of cytokines, such as IL-1, IL-6, IL-12, IL-23, TNF-α, NO and ROS." (PMID 40303994, 2025). "In response to higher levels of HA synthesis and fragments in tumor-associated cells, neutrophils and macrophages produce pro-inflammatory cytokines (IL-1, IL-6, IL-22, and TNF-α) which predispose individuals to cancer mutations." (PMID 40723879, 2025). "In the present work, we also observed that agathisflavone was able to positively regulate the expression of the inflammatory cytokine IL-6 and the regulatory factor arginase, associated with increased response against the tumour." (PMID 39795214, 2025). "Gene expression of IL-6 and IL-23 was markedly upregulated in tumor tissues and significantly associated with advanced stage (P < 0.001), grade 3 histology (P < 0.001), and hormone receptor-positive status (P = 0.023)." (PMID 40612845, 2025). "The HPV E6/E7 genes suppress CCL20/MIP3α secretion, impairing Langerhans cell migration, while HPV-positive cells secrete elevated levels of G-CSF, IL-6, IL-8, promoting the recruitment of tumor-associated neutrophils and M2 macrophages." (PMID 40264780, 2025). "Inflammatory cytokines (TNF-α, IL-1, IL-6) at tumor sites create a pro-autoimmune milieu where the immune system generates AAb against tumor-associated targets, potentially increasing autoimmune risk." (PMID 41367866, 2025). "It is postulated that the IL-6 generated by the PCC is the culprit behind the fevers since the removal of the tumor, IL-6 levels declined, and the associated symptoms resolved." (PMID 40917352, 2025). "For example, tumor-associated macrophages are pivotal in secreting cytokines such as interleukin-6 (IL-6) and vascular endothelial growth factor (VEGF), which act to promote proliferation and angiogenesis." (PMID 40407535, 2025). "IL-6 also contributes to the activation of cancer-associated fibroblasts via pancreatic stellate cells, key components of the tumor stroma." (PMID 41397158, 2025).
tumor (continued). "Considering the cut-off values previously established for each of them, we observed significant associations between low levels of IL-6 and a lower risk of presenting an unfavorable tumor histology and high levels of IL-6 and a higher risk of death." (PMID 40722593, 2025). "Accumulating evidence has established that IL-6 plays a pivotal role in cancer-associated inflammation, and overexpression of IL-6 in the tumor site and increased circulating level of IL-6 are related with poor clinical prognosis in multiple types of cancer." (PMID 40255422, 2025). "IL-6, a cytokine with many roles, is typically present in a range of tumor microenvironments and has been associated with tumor development and therapeutic resistance across multiple cancer types, primarily through its modulation of the immune system." (PMID 41162970, 2025). "M2d cells (tumor-associated macrophages, TAMs), stimulated by IL-6 and adenosine, promote angiogenesis and tumor progression." (PMID 40940785, 2025). "Tumor-associated macrophages (TAMs) play a crucial role in tumor progression by secreting proinflammatory cytokines (e.g., IL-1, IL-6) and proteolytic enzymes, further exacerbating liver injury." (PMID 41357571, 2025). "Stromal components, such as cancer-associated fibroblasts and tumour-associated macrophages, secrete IL-6 and activate the STAT3 and NF-κB pathways in cancer cells." (PMID 40806254, 2025). "It was suggested that IL-6 levels in tumour-associated endothelial cells correlate with the tumourigenicity of CSCs, as evidenced in vitro by the p-STAT3 activation, survival, and self-renewal of human CSCs." (PMID 41009413, 2025). "Pathogenic Th17 cells produce IL‐17 and IL‐6, which contribute to tissue damage, inflammation, and ultimately oncogenesis by promoting tumor cell survival, proliferation, angiogenesis, and metastasis." (PMID 41384027, 2025). "For example, tumor cells can cause neutrophils in the premetastatic niche to transform to N2 by secreting IL‐6, IL‐10, G‐CSF, and TGF‐β into the premetastatic niche or by inducing cells in the premetastatic niche to produce these chemokines." (PMID 40979214, 2025). "IL‐6 is a proinflammatory cytokine implicated in tumor progression and resistance to anticancer therapies." (PMID 41189442, 2025). "M2d macrophages, also known as tumor-associated macrophages (TAMs), are primarily activated by adenosine or IL-6." (PMID 40034694, 2025). "In a KRAS-driven murine model of NSCLC and human cell lines, STK11-mutated tumours overproduced IL6, CXCL-7, and G-CSF, known as pro-inflammatory cytokines, which determine the accumulation of neutrophils with T-cell suppressive function." (PMID 40650126, 2025). "In contrast, the overexpression of Nrf2 and HO-1 in NSCLC cell lines, such as NCI-H292, SK-MES-1, and NCI-H460, promotes the expression of thymidine phosphorylase, IL-6, and IL-1β and subsequently facilitates tumor-associated angiogenesis." (PMID 40722961, 2025). "In BC, tumor cell‐derived exosomal circSERPINE2 can be absorbed by tumor‐associated macrophages (TAMs), enhancing their IL‐6 secretion." (PMID 39901896, 2025). "For instance, IL-6 produced by senescent tumor-associated fibroblasts facilitated EMT and chemoresistance in oral squamous cell carcinoma (OSCC), a major subtype of HNCs, through activation of the JAK/STAT3 pathway." (PMID 41463272, 2025). "It interacts with immune cells, including macrophages and lymphocytes, and regulates cytokine-mediated signaling, particularly involving interleukin-6 (IL-6) and interleukin-8 (IL-8), which promote tumor-associated inflammation and immune suppression." (PMID 41426339, 2025). "Elevation of IL1α activated IL6–STAT3 signaling pathway together with IL6 caused neutrophil accumulation in Kras/Lkb1 tumor microenvironment." (PMID 41254689, 2025).
tumor (continued). "Elevated IL-6 has also been linked to aggressive tumor features such as larger tumor size, high grade, and hormone-receptor negativity in some studies, which was consistent with an inflammatory phenotype often seen in triple-negative and HER2+ tumors." (PMID 41007766, 2025). "This indicates that IL-6 plays an important role in inducing M2 polarization of tumor-associated macrophages (TAMs)." (PMID 40429988, 2025). "In contrast to CD28 signaling, SLAMF7 engagement reduced IL-10 secretion, a cytokine with well-established immunosuppressive functions, as well as IL-6 levels, which has been implicated in inflammation-driven tumor progression." (PMID 40909279, 2025). "Elevated circulating levels of IL-6 were associated with an unfavorable tumor histology, and low serum levels of both IL-6 and IL-8 were associated with a lower risk of death." (PMID 40722593, 2025). "For instance, tumor-associated macrophages (TAMs) secrete pro-inflammatory cytokines such as IL-6 and TNF-α, triggering neuroinflammatory responses." (PMID 40276074, 2025). "FABP4 is also expressed in M2-like tumor-associated macrophages and plays a critical role in pro-tumor activity by promoting the IL-6/signal transducer and activator of transcription (STAT)-3 signaling pathway in a murine breast cancer model." (PMID 40017805, 2025). "STAT-3 activation via IL-6 is associated with more aggressive tumor behavior, worse outcomes, shorter survival times, and more advanced NMIBC." (PMID 40227644, 2025). "Within the TME, IL-6 predominantly drives macrophages toward an M2 phenotype, a state that is intimately linked to immunosuppression and the facilitation of tumor growth and metastasis." (PMID 40109347, 2025). "Tumor RNA-seq analyses across multiple DLBCL cohorts consistently demonstrated that elevated IL-10/IL-6 expression ratios were associated with poorer clinical outcomes." (PMID 40881684, 2025). "ELISA assays performed on tumor-associated immune cell supernatants revealed that IL-6 and TNF-α secretion was significantly increased in the Bacilli group." (PMID 40693141, 2025). "Significant T-cell expansion and activation; poorer PFS linked to elevated tumor-promoting cytokines (e.g., TNFα, IL6)." (PMID 40433369, 2025). "In GBM, tumor-associated endothelial cells induce HIF-2α-dependent upregulation of Arg1 expression through secretion of IL-6, thereby promoting M2 polarization of TAMs and facilitating cancer progression." (PMID 40453088, 2025). "The levels of IL-6 appeared closely associated with the patient’s physical status, radiotherapy, and tumor control." (PMID 41476977, 2025). "Elevated CRP levels serve as a direct marker of activation of the IL-6 signaling pathway, which has been implicated in promoting tumor cell survival, proliferation, and chemotherapy resistance." (PMID 41586228, 2025). "A positive correlation was observed between tumor grade and salivary levels of sCD44, IL-6, and IL-8, with the strongest association seen for sCD44, followed by IL-6 and IL-8." (PMID 40924302, 2025). "The JAK/STAT3 signaling pathway through IL-6 signaling causes cells to undergo EMT whichresults in the advancement of tumor spread and invasion." (PMID 40978585, 2025). "M2d macrophages, often equated with tumor-associated macrophages (TAMs), are induced by IL-6 and adenosine signaling within the tumor microenvironment." (PMID 40821768, 2025). "The tumor inflammatory microenvironment is characterized by the extensive infiltration of inflammatory cells such as tumor-associated macrophages and neutrophils, and the massive expression of inflammatory cytokines such as IL-6 and IL-811." (PMID 39990658, 2025).
tumor (continued). "It has also been studied that high levels of IL-6 are present in the tumor microenvironment of HNSCC, which is associated with poor prognosis and higher mortality in HNSCC patients." (PMID 41479792, 2025). "IL-6 is produced by various cells in the tumor microenvironment, including tumor cells, cancer-associated fibroblasts, and especially tumor-associated macrophages (TAMs) and other immune cells." (PMID 41007766, 2025). "IL-6 was discovered to be overexpressed in BC patients’ blood and tumor sites, which is often associated with poor prognosis and decreased survival." (PMID 40933989, 2025). "In particular, higher tumor load has been associated with elevated levels of inflammatory biomarkers such as IL-6, ferritin, and IL-8, reflecting an enhanced systemic inflammatory response." (PMID 40362613, 2025). "In a similar vein, mice that lack IL‐6 in bone marrow‐derived cells or are IL‐6‐deficient show fewer tumors and a lower tumor burden." (PMID 40548181, 2025). "Interleukins, such as IL-6 and IL-8, are often found in elevated levels within tumor tissues and are associated with the promotion of a pro-tumorigenic microenvironment." (PMID 40433410, 2025). "GM-CSF, G-CSF, VEGF, M-CSF, and IL-6 are all key cytokines that can be linked to osteosarcoma therapy due to their roles in immune regulation, inflammation, and tumor growth." (PMID 40109854, 2025). "Increased levels of Interleukin 6 (IL-6) and Interleukin 8 (IL-8) are detected, indicating a pro-inflammatory environment associated with tumor progression and metastasis." (PMID 39962817, 2025). "The influence of NF-κB extends beyond tumor cells: in cancer-associated fibroblasts (CAFs), radiation induces secretion of pro-inflammatory cytokines (e.g., IL-6, IL-1β, TNF-α) in an NF-κB-dependent manner, creating a supportive niche for tumor cell survival." (PMID 40725389, 2025). "Laboratory evidence has linked exposure to local anesthetics with decreased vascular endothelial growth factor expression, reduced release of proinflammatory cytokines such as interleukin-6, and diminished activity of tumor-associated macrophages." (PMID 41426844, 2025). "Elevated CRP levels reflect tumor-associated inflammatory responses, often mediated by interleukin-6 and other cytokines, while hypoalbuminemia indicates nutritional compromise, catabolic stress, and chronic systemic inflammation." (PMID 40565984, 2025). "In contrast, iCAFs exhibit a secretory phenotype, producing high levels of inflammatory cytokines such as interleukin‐6 (IL‐6) and IL‐8, thereby modulating immune cell recruitment and tumor‐associated inflammation." (PMID 40656546, 2025). "Our study showed that EIN supplementation was associated with a significant reduction in IL-1 and IL-6 levels, both key pro-inflammatory cytokines involved in tumor-promoting inflammation." (PMID 41387645, 2025). "Previous studies have highlighted IL-1β, IL-6, and IL-8 as key mediators of tumor-associated inflammation, with IL-1β expression correlating with disease progression and survival in molecularly defined NSCLC subgroups." (PMID 41303495, 2025). "Elevated IL-6 levels have been associated with larger tumor size, advanced tumor stage, metastasis, poor prognosis, and increased recurrence risk in esophageal cancer, multiple myeloma, and renal cell carcinoma, among others." (PMID 41007818, 2025). "CRP reflects tumor-associated inflammatory activity and interleukin-6 levels, while serum albumin serves not only as an indicator of nutritional status but also as a surrogate marker of catabolic stress and physiological reserve." (PMID 40565984, 2025). "Extracellular acidosis, a hallmark of aggressive tumours driven by a dysregulated metabolism, worsens OS progression by enhancing IL-6 secretion by MSC via the NF-κB inflammatory pathway." (PMID 41029717, 2025).